TYK2 (tyrosine kinase 2)
Diseases named in the same sentence as TYK2 in open-access papers (continued):
Sharing a sentence is not in itself a finding about the gene and the disease.
infection (60 papers, 2010 to 2026). The state of being infected such as from the introduction of a foreign agent such as serum, vaccine, antigenic substance or organism. "Conceivably, autosomal recessive complete TYK2 deficiency predisposes to severe recurrent infections." (PMID 39835539, 2025). "Rag2-/-Tyk2-/- and Rag2-/-Tyk2K923E mice showed a comparable fungal burden in the skin as Rag2-/- control animals on day 4 p.i, as well as similar infection-associated changes in the white blood cell composition." (PMID 39622833, 2024). "In a recent Mexican study, two tyrosine kinase 2 (TYK2) variants related to infection risk were shown to be protective against SLE." (PMID 38914753, 2024). "Surprisingly, the presence of the necrotic cell layer around the wound in both Tyk2- and Ifngr1-deficient mice correlates with better fungal containment at the infection site and impaired fungal dissemination to kidneys." (PMID 39622833, 2024). "In mice, elimination of Tyk2 produces immunological dysfunctions making the mice highly susceptible to infections and some tumors." (PMID 34439323, 2021). "SLE protection was associated with TYK2 risk infection variants affecting residually its catalytic domain, rs12720356 (OR = 0.308; p = 0.041) and rs34536443 (OR = 0.370; p = 0.034), but not with rs2304256, rs12720270, and rs280500." (PMID 31434951, 2019). "Even though Tyk2-deficient mice respond normally to IL-6 and IL-10 against infections, they require higher IFN-α concentrations to respond in the absence of Tyk221." (PMID 31434951, 2019). "Nampt mRNA synthesis was investigated in mCMV infected wild-type and Tyk2-deficient BMDM at 1–1.5 h post-infection and at 6–6.5 h post-infection." (PMID 30886604, 2019). "In Vero cells, which lack genes encoding type I IFNs, hMPV infection also induced Jak1 and Tyk2 degradation, indicating that this effect is directly induced by the virus and is not IFN-β-dependent." (PMID 21949722, 2011). "Moreover, homozygosity for common TYK2 missense variants, including variants encoding catalytically inactive TYK2, impairs IL-23-dependent IFNγ production and predisposes patients to infections with Mycobacterium tuberculosis." (PMID 39622833, 2024). "Moreover, Tyk2-/- and Tyk2K923E mice recovered faster from the infection-induced body weight loss than control mice." (PMID 39622833, 2024). "The potential for negative selection of this polymorphism over time is also an important avenue of exploration in light of the recent discovery of a common TYK2 variant and its role in enhancing susceptibility to severe infection by historically important human pathogen mycobacterium tuberculosis." (PMID 37770424, 2023). "To investigate the hypothesis that individuals carrying the P1104A, A928V or I684S variants might be at increased risk of serious infection due to partial inhibition of TYK2, we used a comprehensive set of infection-related ICD9 codes developed and validated elsewhere." (PMID 25849893, 2015). "The JAK family member TYK2 is well known for its regulation of inflammation and immunity to infection and cancer." (PMID 40025196, 2025). "Collectively, these results indicate that intradermal infection with C. albicans induces an IFN response in skin-infiltrating neutrophils that requires active TYK2 signaling." (PMID 39622833, 2024). "In WT mice, C. albicans spread throughout the skin, whereas fungi remained more contained at the infection site in Tyk2-/- and Tyk2K923E mice, which only showed a few C. albicans hyphae penetrating the deeper layer of the skin." (PMID 39622833, 2024). "Transcriptomic analysis revealed TYK2’s pivotal role in regulating interferon-inducible genes in neutrophils, thereby impacting their antifungal capacity during infection." (PMID 39622833, 2024). "Overall, these results demonstrate that TYK2 signaling promotes local C. albicans growth and fungal dissemination to kidneys and delays the recovery from the infection." (PMID 39622833, 2024).
infection (continued). "Conversely, TYK2 overexpression by infection with lentivirus containing TYK2 increased endogenous tau levels." (PMID 39528671, 2024). "An association with a TYK2 variant has been identified, which is particularly interesting, given the key role of TYK2 in infection and immunity." (PMID 37196358, 2023). "We and others have established that IL-12- or IL-23-activated TYK2 is central to the production of IFNγ during immunity to tumors and to infections as well as during inflammation." (PMID 31936322, 2020). "They established that TYK2 is required for the immune response to infections and cancer and for the development of inflammation." (PMID 31936322, 2020). "Gene-targeted mice and hereditary defects of TYK2 in men have established the biological and pathological functions of TYK2 in innate and adaptive immune responses to infection and cancer and in (auto-)inflammation." (PMID 31936322, 2020). "Production of IFN-β was observed only on 5 days after infection in the wide range of pancreatic cells in Tyk2 KO mice." (PMID 25849081, 2015). "Tyk2 KO mice intraperitoneally injected with EMC-D virus exhibited high blood glucose levels exceeding 14 mmol l−1 on the fourth day after infection and the high blood glucose levels persisted thereafter." (PMID 25849081, 2015). "In this study, we showed that infection of airway epithelial cells with hMPV decreased cellular level of Janus tyrosine kinase (Jak1) and tyrosine kinase 2 (Tyk2), due to enhanced proteosomal degradation and reduced gene transcription." (PMID 21949722, 2011). "Huh-7 cells were infected with live MARV or UV-inactivated MARV, treated with IFNα, harvested at different time points post-infection (p.i.)and subjected to western blot analysis to determine the phosphorylation state of Tyk2." (PMID 20084112, 2010). "Moreover, the number and frequency of macrophages at the infection site was similar in WT, Tyk2-/- and Tyk2K923E mice." (PMID 39622833, 2024). "Further, total TYK2 levels were unchanged between a WT and ΔUL138STOP infection." (PMID 37289831, 2023). "Typically, overlap of mycobacterial and viral phenotypes occurs where the defective signaling molecule is shared by both pathways, for example in TYK2 or STAT1 deficiency, although the degree of infection susceptibility depends on how and to what extent signaling is impaired." (PMID 36159783, 2022). "JAK1, JAK2, JAK3, and Tyk2 all became more phosphorylated after infection of ST cells by TGEV." (PMID 28642467, 2017). "It is possible that RA-associated TYK2 variants have pleiotropic associations with other phenotypes (e.g., infection), but that our EMR-based approach was not able to detect these associations at the level of statistical significance in our study." (PMID 25849893, 2015). "We found that hMPV-infected cells had more ubiquitinated Jak1 and Tyk2 than mock-infected cells, suggesting the involvement of an ubiquitin-proteasome pathway in the degradation of Jak1 and Tyk2 in the context of hMPV infection." (PMID 21949722, 2011). "Moreover, we show that neutrophil-depletion abolishes the difference in fungal dissemination between WT and Tyk2-/- mice, supporting the conclusion that neutrophils crucially contribute to the better containment of C. albicans at the infection site in Tyk2-/- mice." (PMID 39622833, 2024). "Furthermore, complete loss of function in TYK2 results in recurrent infections linked to these cytokines but not to developmental or homeostatic dysfunction." (PMID 39403378, 2024). "Collectively, these data indicate that the absence of TYK2 does not affect neutrophil recruitment to infection sites but causes the formation of a necrotic neutrophil “barrier” that may trap the fungal pathogen." (PMID 39622833, 2024). "This suggests that altered TYK2 expression may impact immune responses during infection." (PMID 39351231, 2024).
infection (continued). "Interestingly, Tyk2 KO MIP-Tyk2 Tg mice produced IFN-α in the islets □□□□□□□□□□ □□□ □□□□□ □□□□□□, possibly because of high Tyk2 gene expression in pancreatic β-cells, and minimal leukocyte infiltrations on 5 days after infection, escaping from the virus-induced islet β-cell damage." (PMID 25849081, 2015). "To determine whether the inhibitory effect of hMPV infection on IFN-β-induced STAT activation was the result of a disruption in the upstream cellular signaling pathway, we assessed protein abundance of Jak1 and Tyk2 in response to hMPV infection and/or IFN-β treatment." (PMID 21949722, 2011). "Therefore, our results suggest that increased internalization of IFNAR1 following hMPV infection might result from the degradation of Tyk2, which is ligand-independent." (PMID 21949722, 2011). "The PRV UL41 protein, as well as the mRNAs of JAK1, Tyk2, STAT1, STAT2, and IRF9, were detectable in the RIP mixture, signifying that the mRNAs of JAK1, Tyk2, STAT1, STAT2, and IRF9 are among the targets of PRV UL41 during infection." (PMID 41341288, 2025). "Efficient depletion of neutrophils in the blood and skin of WT and Tyk2-/- mice was confirmed with flow cytometry and IHC for NIMP-R14 at day 2 post infection." (PMID 39622833, 2024). "Compared to mock-infected cells, infection with WNV-TX, WNV-MAD, ZIKV MR766, JEV, and DENV-2 all showed a trend of variably decreased JAK1 and Tyk2 abundance." (PMID 32272626, 2020). "In contrast, the TYK2 gene showed significant upregulation in comparison to I10 and HJ9 co-infected cells than in infection with EBV or EBV-HB1 only." (PMID 32993565, 2020). "Quantification of band intensity across three independent experiments demonstrated that significant decreases in both JAK1 and Tyk2 occurred during WNV-TX and ZIKV MR766 infection, whereas only decrease in Tyk2 abundance was significant for JEV." (PMID 32272626, 2020). "Overall, the presently available data suggest that although most immune genes have been under positive selection in the indigenous population, due to several epidemic episodes after the Spanish conquest, variants within TYK2, failing to respond to infections, may have been under negative selection." (PMID 31434951, 2019). "We show that the absence of TYK2 does not impact the initial recruitment of neutrophils to the infection site but results in the accumulation of necrotic neutrophils organized in a barrier-like structure that surrounds the fungal cells." (PMID 39622833, 2024). "In the absence of TYK2 or its kinase activity, these infection-induced changes were less pronounced than in control mice." (PMID 39622833, 2024). "We observed that mice lacking TYK2 or its catalytic activity are more resistant to intradermal infection with C. albicans than wildtype (WT) mice." (PMID 39622833, 2024). "We show that the absence of TYK2 or its catalytic activity decreases dissemination of C. albicans to kidneys in response to intradermal infection and facilitates wound healing and recovery from the infection." (PMID 39622833, 2024). "We show that in the absence of catalytically active TYK2, C. albicans remains locally contained at the infection site and does not invade deep skin layers or disseminate to kidneys." (PMID 39622833, 2024). "These variants were found in inflammasome genes (NLRP1/3 and CASP1), genes mediating inflammasome inactivation via auto- and mitophagy (RIPK2 and MEFV), and genes involved in the response to infection with DNA viruses (POLR3A, DHX58, and IFIH1) and type-1 interferons (TYK2 and PTPRC)." (PMID 37626706, 2023). "Besides these three kinases, network enrichment analysis highlighted the general importance of kinases in infection development, e.g. JAK1, LYN, TYK2 and PRKCZ." (PMID 36579860, 2023). "The increased levels of this affected TYK2 may result in less ISG induction, leading to greater viral replication and more severe infection." (PMID 35739459, 2022).
infection (continued). "These variants were found in inflammasome genes (NLRP1/3, CASP1), genes mediating inflammasome inactivation via auto and mitophagy (RIPK2, MEFV), and genes involved in response to infection with DNA viruses (POLR3A, DHX58, IFIH1) and to type-1 interferons (TYK2, PTPRC)." (PMID 31235738, 2019). "In our study, Tyrosine kinase 2 (TYK2, one of the JAKs) and its negative regulators SOCS1, SOCS3 as well as anti-apoptosis genes BCL-XL and PIM1 were differentially regulated by IRF7 during the H6N2 infection." (PMID 30356848, 2018). "During early infection (within 24 h in cell culture), the virus blocks the phosphorylation and nuclear translocation of STAT1; however, during late infection, the virus modulates the IFN-1 response by inducing the downregulation of JAK1 and Tyk2 protein expression." (PMID 27367734, 2016). "Immunohistochemical study revealed that Tyk2 WT mice had mild CD45-positive leukocyte infiltration with increased IFNα and upregulation of class I major histocompatibility complex (MHC) in 3 days after infection in the islets." (PMID 25849081, 2015). "Jak1 and Tyk2 degradation was viral-replication dependent, as infection with UV-inactivated hMPV failed to affect Jak1 and Tyk2 cellular levels." (PMID 21949722, 2011). "However, when LGTV infection occurred prior to IFN addition, phosphorylation of STAT1, STAT2, Tyk2, and Jak1 were all inhibited, suggesting that LGTV must establish a productive infection to counteract the IFN response." (PMID 21994750, 2011). "This requires careful consideration of the administration of JAK inhibitors (or TYK2 inhibitors) in the context of inhibiting IL-6-mediated inflammatory responses, as the IFN-I responses are not supposed to be suppressed due to their positive roles in early infection." (PMID 34001144, 2021). "For example, STAT1 and tyrosine kinase 2 (TYK2) did not influence infection alongside other positive regulators of IFN signaling, which we attribute to the fact that some gRNAs in the library may have not efficiently directed Cas9 to cut at their respective target gene loci." (PMID 39316623, 2024). "Similarly, infection with live, but not UV-inactivated virus, led to significant reduction of Jak1 and Tyk2 cellular levels, indicating that inhibition of Jak/STAT pathway is dependent on viral replication and gene transcription, which is lost upon UV irradiation." (PMID 21949722, 2011). "Interestingly, infection of cells with UV-inactivated MARV prior to IFNα treatment did not lead to the inhibition of Tyk2 phosphorylation, supporting the assumption that receptor binding does not play a role in the MARV-specific inhibition of the IFN signaling cascades." (PMID 20084112, 2010). "The results showed that FCV 2280 infection contributed to the decrease of JAK1 and Tyk2 phosphorylation but did not reduce the expression levels of total JAK1 and Tyk2." (PMID 33075108, 2020). "In our study, we observed that treatment with BCP-DHA, regardless of the presence of infection, negatively regulated the gene expression of IL-2, IL-6, IRF7, NLRP3, and TYK2, acting directly in NF-ĸB inhibition and the synthesis and activity of pro-inflammatory cytokines." (PMID 36357780, 2022). "Whilst infection of monocytes with EBV for 20 hours led to the phosphorylation of Jak1, STAT1 but not Tyk2 nor STAT2, increased phosphorylation of these proteins could not be observed upon restimulation of infected cells with IFNα." (PMID 20689596, 2010).
tumor (55 papers, 2011 to 2026). "Mouse models for hematopoietic malignancies and our data from the autochthonous CRC model suggest that TYK2-deficient immune cells exhibit impaired tumor immunosurveillance." (PMID 40991399, 2026). "In parallel, JAK1 and JAK2 hyperactivation is commonly linked to cytokine-driven signaling that sustains tumor growth, while TYK2 shows dual behavior: supporting immune surveillance in some contexts but fostering immune evasion in others." (PMID 41438753, 2025). "Recent studies suggest that extracellular HSP90α induces MyD88-IRAK complex-associated IKKα/β-NF-κB/IRF3 and JAK2/TYK2-STAT-3 signaling pathways in macrophages to promote tumor M2 polarization." (PMID 36158677, 2022). "Another study demonstrated that tumor growth and metastasis was enhanced in TYK2-deficient mice owing to the activation of myeloid-derived suppressor cells (MDSCCs)." (PMID 36531252, 2022). "Macroscopic and histologic analysis of formalin-fixed colon tissues revealed increased tumor burden in all three Tyk2-deficient mouse strains." (PMID 36185806, 2022). "The expression of TYK2 was positively associated with the population of tumor-infiltrating immune cells, expression of immune checkpoint genes, and antitumor drug susceptibility." (PMID 36531252, 2022). "In some settings, TYK2 appears to play a role in suppressing tumor growth, and a few studies have reported lower TYK2 expression or loss-of-function (LOF) mutations associated with cancer development or progression." (PMID 34439323, 2021). "TYK2 deficiency reduces MPNST tumor growth through decreased proliferation and increased apoptosis mediated via lower phosphorylated STAT3 (p-STAT3) and BCL-2 with a concomitant increase in caspase 3 cleavage." (PMID 34439323, 2021). "Administration of exogenous IL-15/IL-15Rα to Tyk2-deficient mice restores NK-cell maturation and NK cell-dependent control of tumor growth." (PMID 31936322, 2020). "Although TYK2-dependent cytokines have been implicated in a plethora of processes in anti-tumor immunity, the consequences of TYK2 deficiency on tumor immunity are only beginning to emerge." (PMID 31936322, 2020). "The high susceptibility of Tyk2−/− mice to lymphoid tumors is the result of an impaired tumor surveillance, in particular, a decreased cytotoxic capacity of NK/NKT and CTL cells." (PMID 31936322, 2020). "Without providing molecular details, a mouse model for aggressive lymphoma showed reduced tumor cell invasiveness upon loss of TYK2." (PMID 31694222, 2019). "This raised the question whether the reduced immune infiltration in metastases of TYK2-deficient host mice is directly due to TYK2 deficiency or is an indirect consequence of increased tumor burden." (PMID 40991399, 2026). "The qualitative differences in tumor formation in the three mouse models could be due to differential infiltration and activation of immune cells modulated by loss of Tyk2 in both the hematopoietic system and the epithelial cancer cell compartment." (PMID 36185806, 2022). "It remains to be shown whether this Tyk2 allele affects tumor immunosurveillance." (PMID 40991399, 2026). "The association between the expression of TYK2 and the tumor immune microenvironment, immune checkpoints, and drug sensitivity was explored various packages in R. Cell function assays were finally used for exploring the effects of TYK2 on the growth and metastasis of HNSCC tumors." (PMID 36531252, 2022). "JAK2 (tyrosine kinase 2) promotes tumor growth and treatment response in OS by regulating cell proliferation and immune response." (PMID 41158757, 2026).